CMKLR1 (chemerin chemokine-like receptor 1)
Diseases named in the same sentence as CMKLR1 in open-access papers (continued):
Sharing a sentence is not in itself a finding about the gene and the disease.
lung diseases (3 papers, 2011 to 2024). "Our investigation supports the potential of CMKLR1 as an imaging biomarker for endotyping and risk stratification of fibrotic lung diseases." (PMID 38896611, 2024). "A mouse line invalidated for ChemR23 (Cmklr1) was used previously to investigate the role of chemerin and its receptor in the mounting of anti-viral responses and as an anti-inflammatory system in lung diseases." (PMID 31803622, 2019). "In the present study, we investigated the potential of CMKLR1-targeted PET to monitor the kinetics of MDMφ accumulation in a murine model of fibrotic lung injury and to determine the clinical relevance of CMKLR1 as a biomarker for endotyping and prognostication of fibrotic lung diseases." (PMID 38896611, 2024).
periodontitis (3 papers, 2017 to 2024). An acute or chronic inflammatory process that affects the tissues that surround and support the teeth. "CMKLR1-transfected L1.2 cells migrated to GCF from gingivitis patients (4.2%) but showed little migration to GCF from periodontitis individuals (0.5%)." (PMID 28424689, 2017). "Gingival crevicular samples from patients with gingivitis but not periodontitis contain abundant bioactive chemerin capable of inducing CMKLR1-dependent leukocyte migration." (PMID 28424689, 2017).
skin tumors (3 papers, 2019 to 2022). "The B16 and LLC graft models bypass however the slow progression of naturally occurring tumors, and the fact that CMKLR1-deficient mice display a high frequency of spontaneous skin tumors suggests that the endogenous chemerin production may indeed counteract tumor development in natural situations." (PMID 34548907, 2021). "We reported previously that, in a chemical model of skin carcinogenesis, CMKLR1 deficiency had similarly no consequences, but that CMKLR1 KO mice developed spontaneous tumors of the skin." (PMID 34548907, 2021).
aortic atherosclerosis (2 papers, 2014 to 2021). A atherosclerosis that involves the aorta. "A positive correlation was also noticed between foam cell CMKLR1 expression and aortic atherosclerosis (r=0.424, p=0.012)." (PMID 24779513, 2014). "CMKLR1 immunostaining in foam cells was statistically significantly correlated with aortic atherosclerosis." (PMID 24779513, 2014). "Several correlations were observed between chemerin and CMKLR1 expression in aortic samples and the severity of aortic atherosclerosis." (PMID 24779513, 2014). "When controlling for BMI, partial correlations between periaortic fat chemerin (ρ=0.793, p < 0.001), aortic VSMC chemerin (ρ=0.587, p < 0.001), aortic foam cell chemerin (ρ=0.711, p < 0.001) and aortic foam cell CMKLR1 (ρ=0.434, p=0.012) expression and aortic atherosclerosis remained strong." (PMID 24779513, 2014).
asthma (2 papers, 2024 to 2025). "Chemotaxis of macrophages, NK cells, and myeloid and plasmacytoid dendritic cells are dependent, in part, on CMKLR1, and each of these cells contribute to the pathogenesis of asthma." (PMID 38631890, 2024). "Accordingly, both RvE1 and chemerin may contribute to inflammatory diseases, including asthma, via signaling through CMKLR1." (PMID 38631890, 2024). "It is conceivable that chemerin‐like receptor 1 (CMKLR1) may limit the severity of O3‐induced asthma exacerbations." (PMID 38631890, 2024). "Because exogenous administration of CMKLR1 ligands decreases the severity of antigen‐induced lung inflammation and AHR, we hypothesized that CMKLR1 limits the severity of lung pathophysiology induced by the non‐atopic asthma stimulus, O3." (PMID 38631890, 2024). "In summary, we demonstrate that failure of mice to express CMKLR1 has no impact on the development of lung injury, lung inflammation, or AHR induced by acute inhalation exposure to the non‐atopic asthma stimulus, O3." (PMID 38631890, 2024).
autoimmune disease (2 papers, 2022 to 2023). A disorder resulting from loss of function or tissue destruction of an organ or multiple organs, arising from humoral or cellular immune responses of the individual to their own tissue constituents. "Interestingly, a number of allosteric modulators for C5aR, a close phylogenetic neighbor of CMKLR1, including avacopan, a drug for treating an autoimmune disease, target a similar site right above ICL2 of C5aR." (PMID 38055679, 2023).
diabetic cardiomyopathy (2 papers, 2020 to 2022). Diabetic cardiomyopathy is a disorder of the heart muscle in people with diabetes. "Lately, it has been reported that Cmklr1 axis contributed to the development of diabetic cardiomyopathy on inflammation, which was primarily mediated by Nlrp3 inflammasome." (PMID 35721719, 2022). "Chemerin and its receptor CMKLR1 (a G-protein-coupled receptor) are inducers of inflammation, and play an important role in diabetic cardiomyopathy (DCM)." (PMID 32390873, 2020).
esophageal squamous cell carcinoma (2 papers, 2019 to 2025). Esophageal squamous cell carcinoma (ESCC) is a type of esophageal carcinoma (EC) that can affect any part of the esophagus, but is usually located in the upper or middle third. "Moreover, both patient-derived and commercial (OE21) esophageal squamous cell carcinoma cell lines express CMKLR1, and chemerin secreted by cancer-associated myofibroblasts drives their migration, invasion, and proliferation." (PMID 41301712, 2025). "In esophageal squamous cell carcinoma, chemerin acts as a stromal factor overexpressed by cancer-associated myofibroblasts, recruiting CMKLR1-expressing mesenchymal stromal cells to the tumor microenvironment, thereby fostering a pro-invasive and pro-angiogenic stroma." (PMID 41301712, 2025).
fibrosis (2 papers, 2014 to 2024). the formation of excess fibrous connective tissue in an organ or tissue in a reparative or reactive process. "Here, we validated the accuracy of CMKLR1 as an imaging biomarker of the lung inflammation-fibrosis axis." (PMID 38896611, 2024).
hepatitis C (2 papers, 2016 to 2019). "In hepatitis C infection, hepatic CMKLR1 was normal, levels were reduced or induced in NASH." (PMID 31905933, 2019). "In hepatitis C patients, CMKLR1 mRNA is not related to inflammation and a negative association with fibrosis has been identified in females only." (PMID 27548138, 2016).
hyperandrogenism (2 papers, 2016 to 2022). Excessive secretion of androgens from the adrenal glands or gonads. "DHT levels were significantly elevated in both wild type and CMKLR1 KO mice implanted with DHT-releasing pellets compared with placebo controls, confirming proper establishment of the in vivo hyperandrogenism model." (PMID 26893072, 2016).
Hypercholesterolemia (2 papers, 2016 to 2020). An increased concentration of cholesterol in the blood. "Similarly, CMKLR1 mRNA was unchanged in the 10 patients with NASH and hypercholesterolemia (p = 0.935) and the 17 hypertensive NASH patients (p = 0.367) compared to NASH patients not suffering from these co-morbidities (data not shown)." (PMID 27548138, 2016). "CMKLR1 mRNA was similar in the 14 patients with and those without hypercholesterolemia (data not shown)." (PMID 27548138, 2016).
inflammatory bowel disease (2 papers, 2021 to 2024). A spectrum of small and large bowel inflammatory diseases of unknown etiology. "In a recent report, an antibody agonist that targets CMKLR1 was characterized for its ability to induce an anti-inflammatory phenotype of macrophages, with intended therapeutic use in carcinoma progression and inflammatory bowel disease." (PMID 39595036, 2024).
mesothelioma (2 papers, 2023 to 2024). A usually malignant and aggressive neoplasm of the mesothelium which is often associated with exposure to asbestos. "We report that the expression of ChemR23 coding gene, CMKLR1, in breast and mesothelioma tumors positively correlates to the expression of TAM markers such as CD14, CD163, MRC1 and HLA-DRA, in agreement with ChemR23 detection restricted to macrophages in tumors from patients." (PMID 37539056, 2023).
non-alcoholic fatty liver disease (2 papers, 2020 to 2022). "The chemerin/CMKLR1 axis has been proposed to regulate the activation of the NLRP3 inflammasome in Kupffer cells in a mouse model of nonalcoholic fatty liver disease, and a rat model of limb ischemia/reperfusion-acute lung injury." (PMID 32390873, 2020).
Non-Alcoholic Steatohepatitis (2 papers, 2016 to 2025). "Similarly, in models of nonalcoholic steatohepatitis (NASH), chemerin improves insulin sensitivity by reducing oxidative stress and activating autophagy via the JAK2-STAT3 pathway—effects reversed by CMKLR1 inhibition." (PMID 41457200, 2025).
pulmonary arterial hypertension (2 papers, 2020 to 2024). Pulmonary arterial hypertension (PAH) is a group of diseases characterized by mean pulmonary artery pressure >20 mmHg and elevated pulmonary arterial resistance leading to right heart failure. "Alteration in chemerin signaling has already been linked to other pro-inflammatory conditions or cytokines (including TNF-α, IL-1β, and IL-6) upregulating CMKLR1 and CCRL2 which are also known to play crucial roles in pulmonary artery remodeling in pulmonary hypertension." (PMID 32848866, 2020).
renal fibrosis (2 papers, 2019). A final common manifestation of a wide variety of chronic kidney diseases characterized by glomerulosclerosis and tubulointerstitial fibrosis. "Recent studies showed that CMKLR1 was activated by Wnt/beta-catenin pathway which is involved in accumulation of extracellular matrix (ECM), podocyte dysfunction, and renal fibrosis in DN." (PMID 31379940, 2019).
schizophrenia (2 papers, 2012 to 2019). A major psychotic disorder characterized by abnormalities in the perception or expression of reality. "We found dysregulation of multiple transcripts whose human orthologs are associated with BPD and other psychiatric disorders including schizophrenia and ADHD, including: Epor, Smarca4, Cmklr1, Cat, Tac1, Npsr1, Fhit, and P2rx7." (PMID 22675514, 2012).
Senile plaques (2 papers, 2022 to 2024). Senile plaques are extracellular deposits of amyloid in the gray matter of the brain. "Our data indicate that the chemerin/CMKLR1 axis is involved in the migration and recruitment of microglia to senile plaques via the p38 MAPK pathway." (PMID 36012305, 2022).
aortic aneurysm (1 paper, 2022). A ruptured aneurysm located in the wall of the proximal portion of the descending aorta proceeding from the arch of the aorta. "As CMKLR1 mediates the migration of macrophages and dendritic and NK cells, we speculated that chemerin signaling from VSMCs could active immune cell migration and aggravating aortic aneurysm progression." (PMID 35837612, 2022).
atopic asthma (1 paper, 2024). An asthma that is characterized by symptoms that are triggered by an allergic reaction caused by inhaled allergens such as dust mite allergen, pet dander, pollen and mold. "Accordingly, we quantified sequelae of non‐atopic asthma in wild‐type mice and mice incapable of expressing CMKLR1 (CMKLR1‐deficient mice) following cessation of acute inhalation exposure to either filtered room air (air) or ozone (O3), a criteria pollutant and non‐atopic asthma stimulus." (PMID 38631890, 2024). "Altogether, these data connote engagement of CMKLR1 with either of its ligands decreases the severity and enhances the resolution of atopic asthma." (PMID 38631890, 2024).
autism (1 paper, 2025). Persistent deficits in social interaction and communication and interaction as well as a markedly restricted repertoire of activity and interest as well as repetitive patterns of behavior. "By other hand, miR396 can affect the expression of the CMKLR1 gene, involved in cardiovascular diseases, and the SYVN1 and SCAMP5 genes, changes in the expression of which are associated with colon cancer and autism, respectively." (PMID 40001983, 2025).
breast tumors (1 paper, 2023). "We observed that CMKLR1 was expressed in all subtypes of BC or MPM with a significant lower expression in luminal breast tumors and epithelioid mesothelioma tumors." (PMID 37539056, 2023). "However, using scRNASeq data from breast tumors, we mainly observed an expression of CMKLR1 in a subset of TAM C1QC+ that expressed usual M2 signature, including high expression of CD14 and CD163, whereas CMKLR1 expression was low in a subset of TAM ISG15+ that expressed classical M1 signature." (PMID 37539056, 2023).
Chronic colitis (1 paper, 2023). A chronic inflammatory disease of the large intestine (colon, cecum and rectum). "As to CMKLR1 agonists, several chemerin-derived peptide agonists have been developed, and one CMKLR1 antibody that functions as a receptor agonist was reported to promote inflammation resolution in chronic colitis models." (PMID 38055679, 2023). "However, a recent study has identified an agonist antibody of CMKLR1 that showed promise in inducing chronic resolution of inflammation in animal models with chronic colitis." (PMID 38055679, 2023).
chronic hepatitis (1 paper, 2016). An active inflammatory process affecting the liver for more than six months. "Recently, gender-specific associations of hepatic CMKLR1 expression with liver histology have been identified in chronic hepatitis." (PMID 27548138, 2016).
disc degeneration (1 paper, 2020). "In order to explore, the relationship between disc degeneration and chemerin, as well as CMKLR1, we performed western blotting to detect the NP tissue of patients with disc degeneration of different degrees." (PMID 32526705, 2020).
gastric adenocarcinoma (1 paper, 2019). "The present data support the idea that gastric adenocarcinoma cells express both CMKLR1 and GPR1, and that both play a role in mediating the effect of chemerin on cancer cell migration and invasion." (PMID 30719206, 2019). "We now show that both CMKLR1 and GPR1 are expressed by primary gastric adenocarcinoma cells." (PMID 30719206, 2019).
gastric tumors (1 paper, 2019). "Immunohistochemical studies of gastric tumors identified expression of two putative receptors, chemokine-like receptor-1 (CMKLR1) and G-protein coupled receptor 1(GPR1), in cancer cells; there was also some expression in stromal myofibroblasts although generally at a lower intensity." (PMID 30719206, 2019).
gingivitis (1 paper, 2017). A disorder involving inflammation of the gums; may affect surrounding and supporting structures of the teeth. "Chemerin-mediated chemotaxis, exhibited by the gingivitis samples, may serve to enhance the recruitment of CMKLR1+ cells to inflamed gums." (PMID 28424689, 2017).
glioma (1 paper, 2022). A benign or malignant brain and spinal cord tumor that arises from glial cells (astrocytes, oligodendrocytes, ependymal cells). "Considering that chemerin and TNF-α have been shown to activate NF-κB signaling, which is an important pathway that regulates the mesenchymal features of glioma, we suggest an important role for NF-κB signaling in the chemerin/CMKLR1 axis in GBM." (PMID 35459783, 2022).
hyperparathyroidism (1 paper, 2024). Hyperfunction of the parathyroid glands resulting in the overproduction of parathyroid hormone. "Genetically predicted expression of CMKLR1, PIK3C3, and SLC40A1 retained significant causal associations with hyperparathyroidism risk in GTEx whole blood samples (P < 1.25e−02, inverse-variance weighted methods)." (PMID 38499600, 2024). "Five drug targets (CMKLR1, FSTL1, IGSF11, PIK3C3 and SLC40A1) showed significant causation with hyperparathyroidism in both eQTLGen and GTEx cohorts by MR analysis." (PMID 38499600, 2024).
hypoxic-ischemic encephalopathy (1 paper, 2022). "Moreover, a recent study found that, in a rat model of hypoxic-ischemic encephalopathy, rh-chemerin treatment reverses neurological impairments and alleviates neuronal apoptosis partially through the CMKLR1/CAMKK2/AMPK pathway." (PMID 36012305, 2022).
Infertility (1 paper, 2024). "High levels of chemerin, as a ligand for CMKLR1-expressing monocytes in the blood, provoked local ovarian inflammation, leading to granulosa cell apoptosis, follicular growth arrest, and anovulatory infertility." (PMID 39767764, 2024).
liver fibrosis (1 paper, 2023). "The CMKLR1 protein did not change with age and sex, and moreover, it was not related to tumoral steatosis, inflammation, and liver fibrosis." (PMID 36979716, 2023).
lung adenocarcinoma (1 paper, 2025). A carcinoma that arises from the lung and is characterized by the presence of malignant glandular epithelial cells. "Similar results were seen when examining the tumor expression of CMKLR1 in lung adenocarcinoma, wherein the tumor expression of CMKLR1 was found to be negatively correlated with survival." (PMID 40564073, 2025).
male infertility (1 paper, 2023). The inability of the male to effect fertilization of an ovum after a specified period of unprotected intercourse. "Thus, CMKLR1 may serve as an important immunomodulator driving inflammation and tumor immunity, and its immunological role was first reported in male infertility." (PMID 37152990, 2023).
male reproductive system diseases (1 paper, 2023). "Utilizing the CTD database, we demonstrated that the five hub genes (CD300LB, CMKLR1, CCR4, B3GALT5, and CTSK) significantly affected male reproductive system diseases." (PMID 37152990, 2023).
myeloma (1 paper, 2018). "Stromal cells obtained from myeloma patients and pre-adipocytes produce chemerin, whereas the receptors CCRL2 and CMKLR1 are expressed by myeloma cells." (PMID 29946468, 2018). "Interestingly, primary myeloma cells expressed more CCRL2 and CMKLR1 mRNA compared with multiple myeloma cell lines." (PMID 29946468, 2018).
neuropathic pain (1 paper, 2025). Chronic pain caused by damage to nerve fibers. "Preclinical research in mice has explored modulating the chemerin/CMKLR1 axis, using chemerin-derived peptides or CMKLR1 inhibitors, for potential treatments for neuropathic pain and allergic airway inflammation." (PMID 40969761, 2025).
retinopathy of prematurity (1 paper, 2022). A bilateral retinopathy characterized by neovascularization, scarring, retinal detachment, and eventually blindness. "To determine whether CMKLR1 agonists might be relevant in ocular neovascular diseases, we used a mouse model of oxygen-induced retinopathy (OIR) that closely recapitulates the two phases of retinopathy of prematurity (ROP)." (PMID 34524600, 2022).
rheumatic diseases (1 paper, 2019). "In relation to rheumatic diseases, chondrocytes and SF from RA and OA patients express both chemerin and its receptor chemokine-like receptor 1 (CMKLR1)." (PMID 31443349, 2019).
Sepsis (1 paper, 2016). Sepsis is defined as life-threatening organ dysfunction caused by a dysregulated host response to infection. "Cmklr1 mRNA was significantly decreased in both CD and HFD mice following sepsis (p = 0.001 and p < 0.001, respectively), while Ccrl2 mRNA was increased (p = 0.024 and p = 0.012, respectively)." (PMID 26873079, 2016).
thyroid cancer (1 paper, 2019). "The human protein atlas provides information about CMKLR1 in colorectal, breast, prostate, lung, and thyroid cancer." (PMID 31905933, 2019).